RIGI (RNA sensor RIG-I)
Description:
Innate immune receptor that senses cytoplasmic viral nucleic acids and activates a downstream signaling cascade leading to the production of type I interferons and pro-inflammatory cytokines. Forms a ribonucleoprotein complex with viral RNAs on which it homooligomerizes to form filaments. The homooligomerization allows the recruitment of RNF135 an E3 ubiquitin-protein ligase that activates and amplifies the RIG-I-mediated antiviral signaling in an RNA length-dependent manner through ubiquitination-dependent and -independent mechanisms. Upon activation, associates with mitochondria antiviral signaling protein (MAVS/IPS1) that activates the IKK-related kinases TBK1 and IKBKE which in turn phosphorylate the interferon regulatory factors IRF3 and IRF7, activating transcription of antiviral immunological genes including the IFN-alpha and IFN-beta interferons. Ligands include 5'-triphosphorylated ssRNAs and dsRNAs but also short dsRNAs (<1 kb in length). In addition to the 5'-triphosphate moiety, blunt-end base pairing at the 5'-end of the RNA is very essential. Overhangs at the non-triphosphorylated end of the dsRNA RNA have no major impact on its activity. A 3'overhang at the 5'triphosphate end decreases and any 5'overhang at the 5' triphosphate end abolishes its activity. Detects both positive and negative strand RNA viruses including members of the families Paramyxoviridae: Human respiratory syncytial virus and measles virus (MeV), Rhabdoviridae: vesicular stomatitis virus (VSV), Orthomyxoviridae: influenza A and B virus, Flaviviridae: Japanese encephalitis virus (JEV), hepatitis C virus (HCV), dengue virus (DENV) and west Nile virus (WNV). It also detects rotaviruses and reoviruses. Detects and binds to SARS-CoV-2 RNAs which is inhibited by m6A RNA modifications (Ref.74). Also involved in antiviral signaling in response to viruses containing a dsDNA genome such as Epstein-Barr virus (EBV). Detects dsRNA produced from non-self dsDNA by RNA polymerase III, such as Epstein-Barr virus-encoded RNAs (EBERs). May play important roles in granulocyte production and differentiation, bacterial phagocytosis and in the regulation of cell migration.
Synonyms: RLR-1; RIG-1; RIG-I; DDX58; FLJ13599; DKFZp434J1111; RIG1; SGMRT2
Tractability: Small molecule: a structure with a bound ligand is known; it has a binding pocket of medium quality. Antibody: its Gene Ontology location is reachable by antibodies, with medium confidence; the Human Protein Atlas places it where antibodies can reach. PROTAC: UniProt records ubiquitination sites on it; ubiquitination databases record sites on it.
Gene: Protein-coding gene on chromosome 9 (32,455,302 to 32,526,348, reverse strand). Ensembl gene ENSG00000107201.
Subcellular location: Cytoplasm; Cell projection, ruffle membrane; Cytoplasm, cytoskeleton; Cell junction, tight junction
Subcellular location (Human Protein Atlas): Cytosol; Plasma membrane
Pathways (Reactome):
Immune System: DDX58/IFIH1-mediated induction of interferon-alpha/beta; ISG15 antiviral mechanism; Modulation of host responses by IFN-stimulated genes; NF-kB activation through FADD/RIP-1 pathway mediated by caspase-8 and -10; Negative regulators of DDX58/IFIH1 signaling; OAS antiviral response; TRAF3-dependent IRF activation pathway; TRAF6 mediated IRF7 activation; TRAF6 mediated NF-kB activation
Disease: Evasion by RSV of host interferon responses; RSV-host interactions; SARS-CoV-1 activates/modulates innate immune responses; SARS-CoV-2 activates/modulates innate and adaptive immune responses
Metabolism of proteins: Ovarian tumor domain proteases; Ub-specific processing proteases
Gene Ontology:
Molecular function: ATP hydrolysis activity; double-stranded RNA binding; GTP binding; identical protein binding; pattern recognition receptor activity; protein binding; RNA helicase activity; single-stranded RNA binding; ubiquitin protein ligase binding; zinc ion binding; ATP binding; double-stranded DNA binding; nucleic acid binding
Biological process: antiviral innate immune response; cellular response to exogenous dsRNA; cytoplasmic pattern recognition receptor signaling pathway; defense response to virus; detection of virus; innate immune response; positive regulation of defense response to virus by host; positive regulation of gene expression; positive regulation of granulocyte macrophage colony-stimulating factor production; positive regulation of interferon-alpha production; positive regulation of interferon-beta production; positive regulation of interleukin-6 production; positive regulation of interleukin-8 production; positive regulation of response to cytokine stimulus; positive regulation of transcription by RNA polymerase II; positive regulation of tumor necrosis factor production; regulation of cell migration; RIG-I signaling pathway; positive regulation of myeloid dendritic cell cytokine production; regulation of type III interferon production; response to exogenous dsRNA; response to virus; gene expression; positive regulation of immune system process
Cellular component: actin cytoskeleton; bicellular tight junction; cytoplasm; cytosol; plasma membrane; ribonucleoprotein complex; ruffle membrane; cytoskeleton
Genetic constraint (gnomAD): Loss-of-function variants: 72 observed, 88.89 expected, observed/expected ratio (o/e) 0.81, 90% interval 0.67 to 0.99. The upper end of that interval is the gene's LOEUF score, 0.99, which puts it in group 4 of 6, group 1 being the genes least tolerant of losing a copy. Missense variants: 891 observed, 1,034.5 expected, observed/expected ratio (o/e) 0.86, 90% interval 0.81 to 0.91. Synonymous variants: 309 observed, 347.97 expected, observed/expected ratio (o/e) 0.89, 90% interval 0.81 to 0.98.
Homologues: Orthologues: chimpanzee RIGI (100% identical), macaque RIGI (96% identical), pig RIGI (80% identical), rat Rig1 (78% identical), mouse Rigi (77% identical), guinea pig RIGI (77% identical), rabbit RIGI (76% identical), tropical clawed frog rigi (50% identical), Caenorhabditis elegans drh-3 (22% identical). Paralogues in human: IFIH1 (33% identical), DHX58 (23% identical).
Diseases named in the same sentence as RIGI in open-access papers:
RIGI is named in the same sentence as 273 diseases in open-access papers, as found by Europe PMC text mining. Sharing a sentence is not in itself a finding about the gene and the disease. The quoted sentences say what the papers report.
viral infection (808 papers, 2007 to 2026). "In turn, IFNs induce the production of hundreds of ISGs, including ISG15, IFIT1, and RIGI itself, in a process that aims to control virus infection." (PMID 39403383, 2024). "In this current study, we identified three immune response molecules, which were earlier known to have immunity against viral infection such as RIGI, TLR7, and TLR3." (PMID 34970593, 2021). "These proteins were identified to be strongly induced following viral infection through engaging the RNA sensor RIG-I and increasing signaling through this pathway to enhance the antiviral type I IFN response." (PMID 34484305, 2021). "OASL was identified to be strongly induced following viral infection through engaging the RNA sensor RIG-I and increasing signaling through this pathway to enhance the anti-viral type I IFN response." (PMID 28580319, 2017). "RIGI is necessary for activating innate immunity in response to viral infections." (PMID 32194627, 2020). "Although both RIGI and TLR3 pathways are known to be important for IFN induction by IAV, our experiments showed elevated signaling through the endosomal TLR3 pathway, providing evidence that the WD domain is protective against viral infection." (PMID 40143422, 2025). "Additionally, STING can be activated independent of cGAS during virus infection, such as STING activation by cross-talk with RNA sensor RIG-I-MAVS complex, by virus-induced necroptosis, and by viral envelope mediated fusion process." (PMID 34578409, 2021).
hepatocellular carcinoma (63 papers, 2008 to 2025). A malignant tumor that arises from hepatocytes. "ISGylation of MDA5 results in stabilization of its activated state, whereas RIGI ISGylation resulted in the decreased stability of nonconjugated RIGI and decreased downstream signaling in hepatocellular cancer cells." (PMID 39159817, 2024).
breast carcinoma (53 papers, 2015 to 2026). "Upon breast cancer cell metastasis, the unshielded RN7SL1 activates the pattern recognition receptor retinoic acid-inducible gene I (RIGI), enhancing tumor growth, metastasis, and resistance to treatment." (PMID 38835784, 2024).
COVID-19 (52 papers, 2020 to 2026). A disease caused by infection with severe acute respiratory syndrome coronavirus 2. "Compared to the CONTROL group, increased mRNA transcription was observed for TLRs 3, 7, 9, RIGI, and NLRP3 in the entire COVID-19 group, while TLR8 was decreased." (PMID 34315957, 2021). "Higher levels of several of these proteins were inversely correlated with viral load, including the cytosolic RNA sensor RIG-I (gene symbol DDX58), chemokines (CCL20 and CCL25), and other proteins (Keratin 19 [KRT19], amphiregulin [AREG]) previously shown to be upregulated in COVID-19 patients." (PMID 36239699, 2022).
ZIKV infection (50 papers, 2016 to 2026). "Zika virus infection is detected by RIGI and IRF3, which cause the release of type I IFN and the overexpression of MHC class I and CEACAM1." (PMID 37242305, 2023). "Furthermore, we showed ZIKV infection fails to induce IRF1 and IRF3 accumulation to the nucleus in absence of the RNA sensor RIG-I, suggesting DNA-PKcs is not a ZIKV sensor receptor." (PMID 36311766, 2022).
psoriasis (24 papers, 2013 to 2025). An autoimmune condition characterized by red, well-delineated plaques with silvery scales that are usually on the extensor surfaces and scalp. "The interferon pathway and antiviral response genes, such as Interferon Induced with Helicase C Domain 1 (IFIHI) and RNA sensor RIG-I (known as DDX58), have also been associated with psoriasis." (PMID 38256115, 2024).
Flavivirus Infections (21 papers, 2010 to 2025). Infections with viruses of the genus FLAVIVIRUS, family FLAVIVIRIDAE. "Flavivirus infections produce virus replicative intermediate dsRNA, which could be detected by the cytoplasmic RNA sensor RIG-I and MDA5." (PMID 27576490, 2016).
ovarian carcinoma (18 papers, 2015 to 2025). A malignant neoplasm originating from the surface ovarian epithelium. "Furthermore, loss of BRCA1 in human ovarian cancer cells suppresses nuclear R-loop formation, resulting in accumulation of RNA-DNA hybrids in the cytoplasm which have the potential to activate RIGI." (PMID 39159817, 2024). "Further highlighting the potential importance of RIGI and MDA5 in ovarian cancer, de Queiroz found that cGAS-STING activation, but not that of MDA5 or RIGI, was impaired in a majority of ovarian cancer cell lines." (PMID 39159817, 2024).
avian influenza (8 papers, 2014 to 2026). Infection of domestic and wild fowl and other birds with influenza A virus. "Binding for H and N antigens was observed for different strains of avian influenza with RIGI, TLR7, and TLR3." (PMID 34970593, 2021). "The binding of RIGI of duck with the neuraminidase H5N1 strain of avian influenza is being depicted with certain domains highlighted." (PMID 34970593, 2021). "The binding of RIGI of duck with the hemagglutinin H5N1 strain of avian influenza is being depicted with certain domains highlighted." (PMID 34970593, 2021). "Molecular docking revealed RIGI, TLR3, and TLR7 as the promising genes conferring antiviral immunity against avian influenza." (PMID 34970593, 2021). "The future outcome for the current study is the possible utilization of the identified disease resistant genes (RIGI, TLR3, and TLR7) for the development of avian influenza–resistant chicken with the identified gene insert from duck through gene editing or a transgenic approach." (PMID 34970593, 2021).
endothelial dysfunction (7 papers, 2013 to 2024). In vascular diseases, endothelial dysfunction is a systemic pathological state of the endothelium (the inner lining of blood vessels) and can be broadly defined as an imbalance between vasodilating and vasoconstricting substances produced by (or acting on) the endothelium. "There is evidence that activation of the viral RNA sensor RIG-I induces endothelial dysfunction, vascular oxidative stress, and the recruitment of innate immune cells." (PMID 37100811, 2023).
HCMV infection (5 papers, 2012 to 2019). "HCMV infection triggers expression of ISG, which the virus counters by impairing the IFN signaling pathway, degrading the double-stranded RNA sensor RIG-I (Retinoic acid-inducible gene I) and “repurposing” ISGs such as Tetherin to enhance rather than restrict viral replication." (PMID 24906157, 2014).
E. coli infection (2 papers, 2018 to 2022). "Our results highlighted the increased expression of the RIGI gene, which is one of the molecules responsible for the transcription factor NFKB1 pathway activation in E. coli infections." (PMID 36552020, 2022).
rosacea (1 paper, 2021). A chronic erythematous skin disorder that affects the face. "In inflamed psoriatic and rosacea skin, the RIGI/MAVS signaling pathway is activated upon recognition of the self nucleic acids by cathelicidin, which leads to activation of a downstream type 1 interferon response and adaptive priming to dendritic cell–mediated T cell activation." (PMID 34048712, 2021).
infection (859 papers, 2006 to 2026). The state of being infected such as from the introduction of a foreign agent such as serum, vaccine, antigenic substance or organism. "We demonstrate that TRIM21 enables the RNA sensor RIG-I to detect infection by an incoming RNA virus and the DNA sensor cGAS to detect infection by a DNA virus." (PMID 26506431, 2015). "Interestingly, ISGs, including IFIT2, CXCL10, RIGI, and Mx1, were also detected very early after infection (4 to 12 hpi)." (PMID 31375585, 2019). "Interestingly, the alternative RNA sensor, RIG-I, was superfluous for IFNβ expression in response to VVΔE3L infection, since IFNβ expression was normal in infected RigI-/- cells." (PMID 26939124, 2016). "Apoptotic markers (caspase-3, Bax, Bcl-2) were analyzed by immunofluorescence and immune genes expression kinetics (TLR3/7, RIGI, MDA5, IL-1β, IL-6, TNFα, IL-10, IFNβ and β-catenin) were measured at defined time points post-infection by RT-qPCR." (PMID 41157617, 2025). "One study found that silencing RIGI in Calu-3 cells abolishes the production of IFN-β and other pro-inflammatory cytokines during infection with SARS-CoV-2." (PMID 36419185, 2022). "It is worth mentioning that in vitro infection of preadipocytes at much lower MOI (0.01) also led to increased Tlr3, RigI, Mda5, Mx,1 and Vip transcript levels." (PMID 32409640, 2020). "Studies in cell culture revealed RIGI and downstream IRF3 activation occurs early in infection and subsequently controlled by HCV NS3/4A later in infection." (PMID 31374104, 2019). "In order to investigate the role of caspase domains in antiviral signaling, we co-expressed FLAG tagged wild type (WT) and CARD deleted RIGI (ΔRIGI) in 293 cells, followed by HPIV3 infection." (PMID 19922606, 2009). "Although the precise molecular mechanism hasn’t been clarified, the possible reasons are as follows: Firstly, The dual-directional regulation of TRIM13 on RIGI and MDA5 may be related to the time course of infection." (PMID 33791238, 2021). "However, after infection with Sendai virus, where the RNA sensor RIG-I is responsible for IFN induction, IFN/ISGs expression was induced, demonstrating that the RIG-I pathway and downstream transcriptional machinery is fully functional in activated T cells." (PMID 24404168, 2014). "Infection of A549 cells with HPIV3 resulted in induction of endogenous RIGI expression (RT-PCR was performed using the following primers: RIGI forward, 5'-GCATATTGACTGGACGTGGCA, RIGI reverse, 5'-CAGTCATGGCTGCAGTTCTGTC) during relatively early infection time frame (8 h-12 h post-infection)." (PMID 19922606, 2009). "Moreover, RIGI was involved in activating both arms (NFκB/TNFα and IRF3/IFNα/β) of innate immunity following HPIV3 infection." (PMID 19922606, 2009). "In order to study the involvement of RIGI in antiviral response stimulation via activation of IRF3/NFκB, we expressed RIGI (FLAG tagged) in 293 cells (these cells does not express majority of endogenous PRRs) and analyzed IFN/NFκB activation following HPIV3 infection." (PMID 19922606, 2009).
tumor (257 papers, 2005 to 2026). "Tumor‐intrinsic IFN activation is mainly dependent on two factors: dsRNA fragments recognized by RIGI‐MAVS signaling and dsDNA fragments recognized by cGAS‐STING signaling." (PMID 39031630, 2024). "Interestingly, the activation of the DNA sensor STING promotes the stemness of CD8+ T cells and enhances the anti-tumour function, in contrast to the activity of the RNA sensor RIG-I which negatively regulates the CD8+ T-cell anti-tumour function." (PMID 39322862, 2024). "Mechanistically, these functions may partially depend on circRNAs’ capability to modulate the activity of the cytosolic RNA sensor RIG-I in the tumor cells." (PMID 36433954, 2022). "This reversal in correlation direction was unique to RIGI and TBL1X; the other five proteins maintained consistent patterns with the DEGs across tumor types (p < 0.05), suggesting a context-dependent shift in regulatory relationships during tumor progression." (PMID 41596598, 2026). "An extended analysis of additional type I IFN inducers showed that NLRC4 expression had the highest correlation overall across the various DC subsets and tumor types, followed by IFIH1, RIGI, TMEM173, and finally ADAR." (PMID 38652550, 2024). "The cytosolic RNA sensor RIG-I, when activated, can enhance the infiltration of immune cells—particularly CD4+ and CD8+ T cells—into the TME by promoting type I interferon (IFN-1) responses, leading to tumor cell apoptosis." (PMID 40317075, 2025). "In primary HGSOC, the recurrent tumor-specific DEG IL7R exhibited a positive correlation with AMBP and HDGF and a negative correlation with FEN1, LRRC25, RIGI, and TBL1X (p < 0.05)." (PMID 41596598, 2026).
bacterial infection (15 papers, 2017 to 2025). "Additionally, RIGI plays a significant role in bacterial infection recognition, aiding in the defense against a broader spectrum of pathogens." (PMID 40510586, 2025).
RIGI also shares sentences with these, for which no sentence is quoted: cancer (176 papers); influenza (109); melanoma (86); autoimmune disease (32); colorectal cancer (17); systemic lupus erythematosus (16); colitis (15); asthma (13); co-infection (13); dengue (13); glioma (13); lung carcinoma (13); nasopharyngeal carcinoma (12); Singleton-Merten Syndrome (12); glioblastoma (11); infectious disease (11); HIV-1 infection (10); acute myeloid leukemia (9); atherosclerosis (9); colon carcinoma (9); gastric cancer (9); liver cancer (9); measles (9); Rotavirus infection (9); viral diseases (9); Aicardi-Goutières syndrome (8); Autoimmunity (8); leukemia (8); pancreatic cancer (8); head and neck squamous cell carcinoma (7).
A further 227 diseases each share a sentence with RIGI in 7 papers or fewer.